KMT2CP4 (lysine methyltransferase 2C pseudogene 4)
Gene: Transcribed unprocessed pseudogene on chromosome 2 (89,622,213 to 89,640,635, reverse strand). Ensembl gene ENSG00000283132.
Diseases named in the same sentence as KMT2CP4 in open-access papers:
KMT2CP4 is named in the same sentence as 1 disease in open-access papers, as found by Europe PMC text mining. Sharing a sentence is not in itself a finding about the gene and the disease. The quoted sentences say what the papers report.
multiple sclerosis (1 paper, 2024). A progressive autoimmune disorder affecting the central nervous system resulting in demyelination. "For multiple Sclerosis, two of the three bb-CpGs found in IGR were placed in the HLA region, and the other (cg26328180) placed between genes (LOC107985911 and KMT2CP4) not related with the disease’s pathogenesis." (PMID 39060467, 2024).